FOXM1 (forkhead box M1)
Diseases named in the same sentence as FOXM1 in open-access papers (continued):
Sharing a sentence is not in itself a finding about the gene and the disease.
asthma (8 papers, 2017 to 2025). "Lastly, FOXM1 expression has been associated with asthma pathogenesis." (PMID 38706568, 2024). "The FOXM1 transcription factor is critical for the proliferation and differentiation of Clara cells during the development of conducting airways, and FOXM1 is associated with asthma." (PMID 30992007, 2019). "In the lung, inhibition of FOXM1 prevents IL-13 mediated goblet cell hyperplasia in murine asthma models." (PMID 40501685, 2025). "In addition to its role in asthma pathogenesis, FOXM1 has been identified as a subsequent target for the MuvB-MYBL2 complex with important roles in mitosis." (PMID 38706568, 2024). "Evidence that FOXM1 plays an important role in the pathological mechanism of allergen-induced lung inflammation and goblet cell metaplasia in asthma includes the following: (i) Ren X and colleagues demonstrated that pulmonary allergen sensitization induces the expression of FOXM1." (PMID 30992007, 2019). "Beyond its role in cell cycle and oncogenic processes, FOXM1 has recently been reported to be involved in epithelial cell differentiation in human skin keratinocytes and pulmonary allergic inflammatory disease contributing to goblet cell hyperplasia in asthma models." (PMID 40501685, 2025). "Therefore, FOXM1 suppression is a promising therapeutic approach in asthma treatment." (PMID 30992007, 2019). "Elevated FOXM1 has been shown in goblet and club cells of an HDM asthma mouse model and in patients with severe asthma." (PMID 36203653, 2022). "In addition, silencing FOXM1 reversed the effect of S1P on ASMC functions, suggesting that targeting this pathway might be a potential treatment for asthma." (PMID 30992007, 2019). "Our data are consistent with published studies demonstrating that deletion of Foxm1 from respiratory epithelial cells or pharmacological inhibition of FOXM1 by RCM-1 compound reduces MUC5AC and prevents differentiation of mucin-producing goblet cells in mouse asthma models." (PMID 29267283, 2017).
cholangiocarcinoma (8 papers, 2018 to 2026). A carcinoma that arises from the intrahepatic biliary tree (intrahepatic cholangiocarcinoma) or from the junction, or adjacent to the junction, of the right and left hepatic ducts (hilar cholangiocarcinoma). "FOXM1 inhibitors, in combination with 5-FU, reduce colony formation, decrease cancer cell migration, and induce caspase-dependent apoptosis in colon and cholangiocarcinoma cancer cell lines." (PMID 38398147, 2024). "In summary, our findings showed the great importance of FoxM1/AKR1C1 signaling pathway in human cholangiocarcinoma." (PMID 34127944, 2021). "Correlation analysis revealed that the cellular level of TESC is correlated with that of FOXM1 in cholangiocarcinoma patients." (PMID 32365487, 2020). "Another signaling of FOXM1 via TGF-α/EGFR-STAT3-TESC was observed in cholangiocarcinoma progression." (PMID 33680951, 2020). "Accordingly, we observed marked upregulation of FOXM1 gene expression in human CCA tumors compared to adjacent tissue in the cancer genome atlas cholangiocarcinoma cohort (TCGA-Chol)." (PMID 29464042, 2018). "5-FU-resistant colon cancer and cholangiocarcinoma cells exhibit high levels of FOXM1 and TYMS." (PMID 38398147, 2024). "These preclinical data imply a role for YAP-mediated chromosomal instability in cholangiocarcinoma, and suggest FOXM1 inhibition as a therapeutic target for CCA." (PMID 29464042, 2018). "In this study, we addressed the role of TESC in cholangiocarcinoma tumorigenesis, finding that the TESC level is markedly elevated in cholangiocarcinoma and involved in FOXM1-mediated tumor development." (PMID 32365487, 2020).
gastric tumors (8 papers, 2016 to 2025). "To identify the mechanisms involved in miR-320a-associated gastric tumor growth, we examined the effect of miR-320a inhibition on FoxM1 and P27KIP1 expression in the tumors." (PMID 27086911, 2016). "FOXM1 overexpression has been shown to drive tumor growth and chemoresistance in GC, making it an attractive therapeutic target in aggressive gastric tumors." (PMID 40862793, 2025). "A study has shown that tanshinone IIA can reduce the expression of FOXM1 in gastric tumors, resulting in a rise in p21 and a decrease in PCNA and Ki-67 proteins, ultimately inhibiting the proliferation of SGC-7901 cells." (PMID 37964867, 2023). "Neck cell differentiation-related group C contained TFs such as Hes1, Pbx1, and Spdef, whereas isthmus progenitor cell-related group D again contained gastric tumor-related TFs such as Dnmt1 and Foxm1." (PMID 37386010, 2023). "We found that silencing of GPC3 induces expression of FoxM1 in gastric tumor cells, and that is abrogated by MEK inhibition." (PMID 27259271, 2016). "Overall, tanshinone IIA could suppress the growth of gastric tumor cells by acting as a mediator of FOXM1." (PMID 37964867, 2023). "The identification of FOXM1 and STAT3 as top MRs in proximal gastric tumors highlights a more proliferative and inflammatory oncogenic program in PGC." (PMID 40862793, 2025). "To verify the relevance of GPC3-mediated regulation of FoxM1 in gastric tumors, we performed IHC staining for GPC3 and FoxM1 in 42 primary samples (Wuhan cohort)." (PMID 27259271, 2016).
head and neck cancer (8 papers, 2021 to 2025). A primary or metastatic malignant neoplasm affecting the head and neck. "We further found that PDK1 expression was also markedly elevated in head and neck cancer, and the expression of PDK1 was significantly and positively correlated with the expression of FOXM1 in patients with head and neck cancer from the TCGA database." (PMID 35656815, 2022). "In this study, we analysed the expression of FOXM1 in a cohort of patients from TCGA with normal mucosa and head and neck cancer." (PMID 35656815, 2022). "We observed that FOXM1 expression was higher in head and neck cancer samples than in the normal mucosa." (PMID 35656815, 2022). "Analysis of the survival curves from data obtained in the TCGA database indicated that patients with head and neck cancer with lower FOXM1 expression had significantly longer survival than those with higher FOXM1 expression." (PMID 35656815, 2022). "Recently, FoxM1 silencing in head and neck carcinoma cells was found to augment cell cycle arrest induced by an Artemisinin derivative, hinting towards the prospective involvement of FoxM1 in the anticancer activities of Artemisinin." (PMID 34900697, 2021). "However, only one prior study revealed that G6PD was modulated by FOXM1 for participating radio-resistance in head and neck cancer." (PMID 33859744, 2021). "A previous study presented evidence indicating that FOXM1 could regulate drug resistance in head and neck cancer cells through Linc-ROR." (PMID 34447693, 2021). "Interestingly, a recent study in head and neck carcinoma hinted towards the possible role of FoxM1 in cell cycle arrest induced by dihydroartemisinin, an Artemisinin derivative." (PMID 34900697, 2021). "For example, FOXM1-induced epigenetic signature may serve as ideal biomarkers for early cancer screening in head and neck carcinoma." (PMID 33892811, 2021). "FOXM1 may also act as a therapeutic target against head and neck carcinoma." (PMID 33892811, 2021). "Furthermore, a study demonstrated that DRP1 modulates FoxM1 expression, which enhances MMP12 transcription by binding to its promoter region in head and neck cancer (HNC) cells." (PMID 41323781, 2025). "Based on the results that FOXM1 was aberrantly expressed in NPC samples and NPC cell lines, and that the expression of FOXM1 could predict the prognosis of head and neck cancer, we hypothesized that FOXM1 participates in the regulation of aerobic glycolysis." (PMID 35656815, 2022).
lymphoma (8 papers, 2013 to 2025). A malignant (clonal) proliferation of B- lymphocytes or T- lymphocytes which involves the lymph nodes, bone marrow and/or extranodal sites. "Genetic network analysis of this set resulted in the independent discovery of FOXM1 as a putative lymphoma gene, providing evidence that our approach uncovered at least one known, biologically meaningful gene." (PMID 24130802, 2013). "Network analysis of six DMB genes frequently confirmed in studies on the DLBCL transcriptome enabled the discovery of FOXM1, the forkhead box M1 transcription factor, as a top candidate lymphoma gene." (PMID 24130802, 2013). "Overexpression of FoxM1 has been reported in various carcinomas and lymphomas/leukemias." (PMID 33603066, 2021). "FOXM1, Plk-1, and EZH2 are all described as interesting therapeutic targets in both DLBCL and MCL, and high expression of these genes is reported to be associated with poor survival in lymphoma patients." (PMID 31740676, 2019). "FOXM1 is a potential therapeutic target in mature B cell tumors and ATF2 has been recently found to be highly disregulated in lymphoma." (PMID 25170874, 2014). "Here, we will illustrate how NetAct infers TF activity on two cases of microarray KD experiments—one case for shRNA KD of FOXM1 and shRNA KD of MYB in lymphoma cells (GEO: GSE17172), and another case for KD of BCL6 on both OCI-Ly7 and Pfeiffer GCB-DLBCL cell lines (GEO: GSE45838)." (PMID 36575445, 2022).
myocardial infarction (8 papers, 2017 to 2026). Gross necrosis of the myocardium, as a result of interruption of the blood supply to the area, as in coronary thrombosis. "Altogether, our findings support the application of AAV9‐induced FOXM1 expression as a novel therapy for patients with acute myocardial infarction to potentially prevent the onset of chronic HF." (PMID 40546121, 2025). "For example, VPA treatments significantly rescue cardiac damage after myocardial infarction, and upregulate the transcription of Foxm1 gene in heart, identifying Foxm1 as a potential key target of VPA." (PMID 40963919, 2025). "The transcriptional expression pattern of FoxM1, Id1, and Jnk3 was also determined in the whole heart following myocardial infarction (MI) injury." (PMID 28011860, 2017). "Moreover, interfering with FoxM1 expression significantly impaired cardiac function, increased infarct size, and reduced neovascularization following myocardial infarction." (PMID 40495143, 2025). "Valproic acid is a deacetylation inhibitor that protects the cardiac function of patients who have experienced myocardial infarction through the Foxm1 pathway, and therefore may also represent a potential therapeutic agent for DCM." (PMID 38699233, 2024). "Conversely, SFRP3 downregulation following myocardial infarction (MI) promotes cardiac fibrosis by inducing EndMT through FOXM1‐mediated activation of Wnt/β‐catenin signaling." (PMID 41541657, 2026). "Interestingly, FoxM1 expression was also significantly elevated in myocardial infarction tissue." (PMID 40495143, 2025). "Future studies will focus on elucidating whether AREG directly induces angiogenesis or acts indirectly by modulating pro-angiogenic factors such as VEGF and FGF, and further investigate the role of the complete signaling cascade, including AREG and FoxM1, in post-myocardial infarction angiogenesis." (PMID 40495143, 2025). "Collectively, these data indicated that Foxm1 overexpression not only attenuated acute myocardial infarction injury, but also prevented ventricle remodeling and infarction expansion after MI." (PMID 30552062, 2019). "In vivo, FoxM1 inhibition increased infarct size, reduced neovascularization, and worsened cardiac function, while reversing the reparative and angiogenic effects of AREG+ Tregs on myocardial infarction." (PMID 40495143, 2025).
acute lymphoblastic leukemia (7 papers, 2015 to 2025). Leukemia with an acute onset, characterized by the presence of lymphoblasts in the bone marrow and the peripheral blood. "A more recent study has clearly linked FoxM1 downregulation by gene silencing or its inactivation using Thio to cell cycle arrest and, subsequently, caspase-dependent apoptosis induction in the B-precursor acute lymphoblastic leukemia cells." (PMID 40628925, 2025). "Jurkat (a T-cell acute lymphoblastic leukemia cell line), which has previously been reported to express a high level of FOXM1, was found to express FOXM1 at a level comparable to that of NPM-ALK + ALCL cell lines." (PMID 31390744, 2019). "Buchner reported that FOXM1 inhibition exhibited a cytotoxic effect on B cells without any effect on normal B cell development and survival and suggested FOXM1 as a therapeutic target for acute lymphoblastic leukemia." (PMID 33633721, 2020).
brain tumor (7 papers, 2010 to 2023). "The observance of the expression of FOXM1 in multiple samples of four types of brain tumors in the GlioVis data portal clearly shows that the highest expression is found in GBM." (PMID 37644431, 2023). "Plumbagin acts as a suppressor of forkhead box M1 (FOXM1), an oncogenic factor in different brain tumor cells." (PMID 36307808, 2022). "FOXM1 is highly expressed in GBM, its expression is significantly higher in GBM than in other brain tumors." (PMID 37644431, 2023).
malignant glioma (7 papers, 2013 to 2025). A grade III or grade IV glioma arising from the central nervous system. "Another study showed that FoxM1 promoted the invasion and disease progression of malignant glioma by enhancing MMP-2 gene transcription." (PMID 30580327, 2018). "Forkhead box M1 (FoxM1) is a member of the forkhead transcription factor family and is overexpression in malignant gliomas." (PMID 23991102, 2013). "In addition, some studies also indicated that ALKBH5 overexpression triggered the development and invasion of malignant glioma by increasing FOXM1 expression products." (PMID 35004726, 2021). "FOXM1 expression was significantly increased in malignant gliomas: DA and GB." (PMID 34131149, 2021). "For example, aberrant FoxM1 expression was a common molecular alteration in malignant glioma." (PMID 23991102, 2013).
metastatic tumors (7 papers, 2007 to 2024). "FOXM1 protein was highly expressed in the cytoplasm in the primary as well as in the metastatic tumors." (PMID 35267428, 2022). "Meanwhile, the level of E-cadherin protein decreased, while the levels of N-cadherin, Snail, Slug, ZEB1, and ZEB2 proteins increased, in metastatic tumors with FOXM1 knockdown." (PMID 32513952, 2020). "Both FOXM1 and RHNO1 were overexpressed in each category of cancer samples (primary tumors, metastatic tumors, and recurrent tumors) as compared to normal tissues." (PMID 33890574, 2021). "Interestingly, FoxM1 is consistently upregulated in metastases, while RDX was upregulated in only two of the four patients with metastatic disease, confirming the heterogeneity of metastatic prostate cancer." (PMID 17430594, 2007).
pneumonia (7 papers, 2015 to 2024). An acute, acute and chronic, or chronic inflammation focally or diffusely affecting the lung parenchyma, caused by an infection in one or both of the lungs (by bacteria, viruses, fungi, or mycoplasma.). "Consistent with the expression trends found in prior studies, we observed a high expression of FOXM1 in the serum of patients with pneumonia and LPS-treated WI-38 cells and mice, indicating that FOXM1 is implicated in the development of pneumonia." (PMID 34301223, 2021). "Overall, FOXM1 overexpression counteracted the protective role of FBXL19 overexpression in lung injury in pneumonia immature mice." (PMID 36964598, 2023). "Increased FOXM1 levels have been observed in lung tissues of patients with newborn hyperoxic lung injury and the serum of patients with childhood pneumonia, which is in accordance with the upregulation of FOXM1 in Spn-induced immature mice in our study." (PMID 36964598, 2023). "Silencing of lncRNA KCNQ1OT1 alleviates lipopolysaccharide-induced lung injury by regulating the miR-370-3p/FOXM1 axis in childhood pneumonia." (PMID 37280583, 2023). "Specifically, FOXM1 can affect inflammation in pneumonia through NF-κB and the JAK/STAT signaling pathway and FOXM1 deficiency reduces the expressions of CCL11, CCL24 and chemokine receptors CCR2 and CX3CR1 to further affect inflammation." (PMID 36964598, 2023). "Nevertheless, future studies are needed to provide compelling evidence for the biphasic pattern of FOXM1 in pneumonia." (PMID 36964598, 2023). "For this reason, we conjectured the biphasic pattern of FOXM1 in pneumonia with an initial adverse role in initiating inflammatory injury and the subsequent role in promoting the recovery and survival after the disease." (PMID 36964598, 2023). "Our results further confirmed the key role of the KCNQ1OT1/miR-370-3p/FOXM1 axis in the progression of pneumonia, providing new ideas for its clinical treatment." (PMID 34301223, 2021). "The regulatory role of the KCNQ1OT1/miR-370-3p/FOXM1 axis in pneumonia was further analysed in a mouse model of LPS-induced lung injury." (PMID 34301223, 2021). "The expression of KCNQ1OT1 and FOXM1 was up-regulated, and miR-370-3p was down-regulated in the serum of children with pneumonia, LPS-treated WI-38 cells, and in lung tissues of LPS-treated mice." (PMID 34301223, 2021). "We offer the first evidence for the regulatory role of KCNQ1OT1 via regulation of the miR-370-3p/forkhead box protein M1 (FOXM1) axis in pneumonia." (PMID 34301223, 2021). "Silencing of KCNQ1OT1 alleviates LPS-induced lung injury by regulating the miR-370-3p/FOXM1 axis in pneumonia." (PMID 34301223, 2021). "The expression of KCNQ1OT1, FOXM1, and miR-370-3p was detected in the serum of 24 children with pneumonia and in 24 healthy controls." (PMID 34301223, 2021). "Up-regulation of FOXM1 has been unveiled in pulmonary allergen sensitisation-induced airway epithelial and inflammatory cells, Pseudomonas aeruginosa-induced pneumonia mice, and patients with bronchopulmonary dysplasia." (PMID 34301223, 2021). "Previously, in an induced pneumonia model, expression of FoxM1 in the knockout mice restored the proliferation and trans-differentiation defects of alveolar epithelium progenitor cells." (PMID 26350477, 2015). "FOXM1 can be modified by ubiquitination and is upregulated in the serum of pneumonia patients." (PMID 36964598, 2023). "Furthermore, overexpression of FOXM1 reversed the protective role of FBXL19 overexpression against lung injury in pneumonia immature mice." (PMID 36964598, 2023). "Interestingly, FOXM1 is elevated in the serum of children with pneumonia and its knockdown retards lung injury and inflammation in vivo and in vitro." (PMID 36964598, 2023).